MMP9 (matrix metallopeptidase 9)
Diseases named in the same sentence as MMP9 in open-access papers (continued):
Sharing a sentence is not in itself a finding about the gene and the disease.
breast carcinoma (continued). "Diltiazem administration in vivo also upregulated the serum level of GDF-15, as well as reduced EMT and MMP-9/MMP-2 expression, leading to a decrease in metastasis of breast cancer." (PMID 36831338, 2023). "GWAS that implicate BNC2-associated alleles with adolescent idiopathic scoliosis also implicate other ECM-associated genes and cytokines that we also find to be under BNC2 control in our breast cancer system (MATN1, MMP9, SOX9, IL-6 as examples)." (PMID 37536977, 2023). "In other breast cancer cell lines, it signals via a Par2—phospholipase C γ2 (PLCγ2)—protein kinase C (PKC) pathway, resulting in the upregulation of NFkB and subsequent mmp9 expression responsible for metastasis." (PMID 37566613, 2023). "In a study with the breast cancer cell line MCF-7, metformin displayed inhibiting effects on MMP9 expression at 5.0 and 10.0 mmol/L after 24 h, whereas MMP2 levels were not affected." (PMID 37313172, 2023). "In ovarian cancer and breast cancer, PGRN increased the invasion of tumor cells by upregulating MMP-2 and MMP-9 proteins." (PMID 37660003, 2023). "GPR176 silencing was shown to reduce the expression of MMP1, MMP9, and VEGF, accounting for the effects of GPR176 in promoting the invasion and metastasis of breast cancer cells." (PMID 37079213, 2023). "Actually, LCN2 has the potential to preserve MMP-9 activity by preventing its degradation, and there is a close relationship between LCN2 expression and MMP-9 activity in a mouse model of breast cancer." (PMID 36798684, 2023). "MMP-9, which was found to be suppressed in the RNA-Seq analysis in this study, is known to promote tumor invasion and angiogenesis by activating TGF-β in breast cancer cells." (PMID 36996146, 2023). "Several in vitro and in vivo studies found that THC and JWH-133, a CB2 agonist, exert anti-proliferative and anti-angiogenic effects on ErbB-2 breast cancer by reducing MMP-2 (Matrix metalloproteinase) and MMP-9 (Matrix Metalloproteinase-9) levels." (PMID 36831374, 2023). "In breast cancer, N-cadherin interacts with fibroblast growth factor receptor (FGFR), activates signal pathways, and induces the expression of matrix metalloproteinase-9 (MMP-9), thereby promoting tumor invasion and metastasis." (PMID 37284201, 2023). "For example, in breast cancer (BC), PNU-74654 can inhibit cell migration and invasion by upregulating E-cadherin and downregulating MMP3 and MMP9, thereby providing a synergistic enhancement of the anticancer effect of fluorouracil (5-FU)." (PMID 37763649, 2023). "Increase in MMP-9 expression in MCF-7 and MDA-MB-231 breast cancer cells exposed to adipocytokines from in vitro differentiated obese adipocytes is correlated with the increase in the development of invasiveness observed in the cells in the current study." (PMID 38068928, 2023). "It is possible that the TMBIM6-induced progression and metastasis of breast cancer can be mediated through MMP-2 and/or MMP-9." (PMID 37057283, 2023). "IL-1β also activates focal adhesion kinase and Src to induce MMP9 production and invasion of MCF-7 breast cancer cells." (PMID 36835413, 2023). "Crp2 absence abrogated synthesis and secretion of Mmp-9 and also the Mt1-Mmp-mediated ECM degradation in breast cancer cell lines." (PMID 38173933, 2023). "In breast cancer cells, KLF9 recruits HDAC1 to the MMP9 (Matrix Metallopeptidase 9) gene promoter to repress MMP9 synthesis and consequent cell migration/invasion." (PMID 38067370, 2023). "DHA has been proven in studies to reduce MMP-9 production and activity in MCF-7 human breast cancer cells by blocking the DNA-binding activity of NF-B and AP." (PMID 38068849, 2023). "In the TCGA dataset, we assessed the expression of key epithelial marker E-cadherin (CDH1) and mesenchymal markers, including vimentin (VIM), MMP9, SNAI2, ZEB1, and ZEB2, about VISTA expression in breast cancer patients using Spearman correlation analysis." (PMID 37152039, 2023).
breast carcinoma (continued). "TBBPA treatment significantly increased the expression of matrix metalloproteinase-9 (MMP-9) and its promoter activity in human breast cancer MCF-7 cells." (PMID 36985477, 2023). "As important biomarkers, matrix metalloproteinase-9 (MMP-9) correlates closely with cancer invasion and is overexpressed within breast cancer tissues, especially in triple-negative breast cancer (TNBC)." (PMID 36978072, 2023). "Hypoxia and the HIF-1 pathway have been shown to upregulate several members of the MMP family in breast cancer, including MMP-2 and MMP-9." (PMID 37266453, 2023). "AG intervention has been shown to attenuate breast cancer cell metastasis and new blood vessel formation in HUVECs via decreasing the expressions of VEGFR, COX-2, ZEB1, p-AKT, and MMP9." (PMID 37920216, 2023). "The upregulation of PODXL, MMP3 and MMP9 are believed to promote cell migration 48-50, suggesting CREB activation is critical for GPT2/GABA-induced breast cancer migration." (PMID 36923530, 2023). "We propose that this is due to the secretion of multiple cytokines that have been shown to increase breast cancer aggressiveness, namely CXCL5, COX-2, MMP-9, and IL-6." (PMID 37760470, 2023). "In breast cancer cells, curcumin inhibited TPA-induced cell invasion and MMP-9 expression by suppressing both NF-κB and AP-1 activation." (PMID 36900342, 2023). "In a mouse model of breast cancer, co-culturing 4T1 cells with RAW264.7 cells in vitro resulted in a significant increase in CHI3L1, LCN2, and MMP-9 levels in serum, which promoted tumor metastasis." (PMID 38003338, 2023). "Further evidence from studies on breast cancer suggests that MDM2 promotes cell motility and invasiveness of breast cancer cells by targeting E-cadherin for degradation and inducing MMP9 expression." (PMID 37138218, 2023). "Those compounds were docked to critically important breast cancer signaling targets such as HER2, COX2, and MMP-9, and the compounds with the lowest binding scores were chosen for comparison." (PMID 37894581, 2023). "For instance, metalloproteases such as MMP-9 or MMP-2 were found to be overexpressed in brain metastases of lung adenocarcinoma cells and breast cancer cells, respectively." (PMID 38072918, 2023). "There is also a positive correlation between the expression of MMP-2, MMP-9, and MMP-11 and breast cancer prognosis." (PMID 37798646, 2023). "Exogenous HRG and MMP proteolytic enzymes (MMP2, MMP9) were shown to enhance the adhesion and TEM across BE in HER2/3-expressing luminal breast cancer cell lines (MDA-MB-361, MCF-7, SKBr3)." (PMID 37190188, 2023). "The study identified 33 common targets of PPIs at the intersection of breast cancer and diabetes, where AKT1 and MMP9 were found to be the core targets." (PMID 37165049, 2023). "Meanwhile, exogenous miR-186-5p mimic in MDA-MB-231 cells significantly inhibited the expression of SBEM, p-PI3K, p-AKT and their downstream pathways, MMP1, MMP3, MMP9, CyclinD1, PCNA and CyclinB1 proteins and reduced proliferation of breast cancer cells." (PMID 37477531, 2023). "IATL inhibits breast cancer cell adhesion, migration, and invasion via the p38 MAPK/NF-κB signaling pathway, and the activity and expression of MMP-2 and MMP-9 are downregulated by IATL in a dose-dependent manner." (PMID 38111074, 2023). "Through down-regulating MMP-9 and increasing TIMP-1, coptisine can suppress adhesion, migration, and invasion of MDA-MB-231 breast cancer cells." (PMID 36831555, 2023). "The activated transcription factor CREB accelerates breast cancer metastasis by upregulating metastasis-related gene expressions, such as PODXL, MMP3, and MMP9." (PMID 36923530, 2023). "Based on these datasets, it can be deduced that ADAM8 enhances precocious metastatic events like transendothelial migration through upregulation of MMP-9 and liberation of PSGL-1 by breast cancer cells." (PMID 36910158, 2023).
breast carcinoma (continued). "Such is the case of the sHH-Gli pathway, which, when inhibited with cyclopamine, decreases breast cancer MDA-MB-231 cells’ invasion and migration, and MMP-2 and MMP-9 concentrations." (PMID 38069210, 2023). "The combined treatment reduced the rate of BC cell migration by 62% and the expression of gelatinase enzymes MMP-9 and MMP-2 genes, which have a key role in the metastasis of breast cancer cells." (PMID 37175156, 2023). "In the clinical diagnosis of high-grade (grade-3) breast cancer, the study showed exuberantly increases MMP-2 and MMP-9 mRNA and protein expression." (PMID 36993955, 2023). "Invading breast cancer cells begin to degrade restrictive extracellular matrix components by expressing matrix metalloproteinases, such as MMP-2 and MMP-9, and similar matrix reconstruction enzymes that lead to widespread breast cancer invasion." (PMID 35208277, 2022). "Qiong and Yin revealed that epirubicin resistance in breast cancer was promoted by an elevated level of orosmucoid 1, which was induced by MMP-2 and MMP-9 upregulation." (PMID 35586209, 2022). "Elevated expression of MMP9 was correlates with more aggressive subtypes of breast cancer, such as TNBC and HER2-positive breast cancer." (PMID 35852149, 2022). "In conclusion, SIRT6 regulated the migration and invasion of breast cancer cells in vitro and played an essential role in TPA- or TNF-α-induced MMP-9 expression." (PMID 35840633, 2022). "Taken together, UA can inhibit against tumor progression during the treatment of breast cancer with Dox, and possibly modulate the Erk-VEGF/MMP-9 signaling pathways and polyamine metabolism by targeting ODC to exert these effects." (PMID 35209071, 2022). "Formononetin, a natural drug and the active component of the herb Astragalus membranaceus, can inhibit the migration and invasion of breast cancer cells by inhibiting MMP-2, MMP9, and PI3K/AKT signaling pathways." (PMID 35463082, 2022). "Statins also block the adhesion, migration and invasion of breast cancer cells by reducing integrin-binding activity and MMP2 and MMP9 activity." (PMID 36139556, 2022). "In highly invasive CD44 expressing breast carcinomas, tumor cells also activate MMP-2 and MMP-9 resulting in degradation of collagen type IV in vascular basement membranes." (PMID 36497364, 2022). "SIPA1 knocked down in breast cancer cells significantly reduced FAK and Akt phosphorylation and inhibited MMP9 extracellular secretion through the integrin-mediated FAK/AKT-MMP9 signaling pathway." (PMID 36230738, 2022). "For example, MMP9, an important enzyme to the degradation of extracellular matrix (ECM), was considered to be an onset of invasion or metastasis in breast cancer." (PMID 35852149, 2022). "This study investigated the effect of SIRT6 on the invasive behavior of two breast cancer cell lines, MCF-7 and MDA-MB-231, as well as the role played by MMP-9." (PMID 35840633, 2022). "The metabolic regulatory roles of MMP9 and the upstream regulatory mechanism of the elevated expression of MMP9 in TNBC and HER2-positive breast cancer require further study." (PMID 35852149, 2022). "Resveratrol remarkably inhibited the activity and expression of MMP-9, and attenuated PI3K activity and phosphorylation of AKT and mTOR in breast cancer cells." (PMID 36142391, 2022). "Diltiazem administration in vivo also upregulates serum level of GDF-15, diminishes EMT and MMP-9/MMP-2 expression, leading to the decrease of lung metastasis of breast cancer." (PMID 35963873, 2022). "The aim of this study was to evaluate the in vitro effect of SalB on the expression and the activity of matrix metalloproteinase 9 (MMP-9), a zinc-dependent proteolytic enzyme, in human MDA-MB-231 breast cancer cells." (PMID 36500603, 2022). "In this work, Epi-Nio-HA successfully reduced the migration of 4T1 and SkBr3 breast cancer cell lines by downregulating the expressions of MMP-2 and MMP-9." (PMID 35875198, 2022).
breast carcinoma (continued). "Paradoxically, in human breast cancer, LCK suppresses cellular invasion by decreasing MMP9, SKP2, and VEGF-A expression but promotes the metastasis of breast cancer." (PMID 36430477, 2022). "Other angiogenic factors such as MMP-2, MMP-9 and IL-6 can also be elevated via the ADRB signaling pathway following stimulation by adrenaline or NA in several breast cancer cell lines." (PMID 35563552, 2022). "According to another experiment, TBG can block breast cancer cell mobility through effectively impeding MMP-2 and MMP-9 synthesis, thereby achieving the inhibition of breast cancer cell proliferation and migration." (PMID 36237327, 2022). "In breast cancer cells, SIRT6 has been related to the upregulation of MMP-920, and SIRT6 knockdown has been shown to reduce MMP-9 expression." (PMID 35840633, 2022). "For example, upregulated expression of TPX2 enhances breast cancer metastasis by mediating MMP2 and MMP9 expression." (PMID 36225568, 2022). "Increased METTL14 and ALKBH5 levels were detected in hypoxia-treated breast cancer cells, which led to upregulation of angiogenic transcripts, including TGF-β, matrix metallopeptidase 9 (MMP9), PDGF, and VEGFA." (PMID 36291060, 2022). "In the present study, azilsartan was found to inhibit the expression of MMP9 protein in both MCF-7 and MDA-MB-231 breast cancer cell lines." (PMID 36431925, 2022). "GBP-2 also inhibits the TNF-α induction of matrix metalloproteinase-9 (MMP-9), known to play a role in breast cancer invasion." (PMID 35681772, 2022). "Although there is no defined correlation of ACKR2 expression with other carcinogenic factors in cervical cancer, ACKR2 downregulation has been accompanied by dysregulation of metastatic factors such as MMP9 and VEGF in breast cancer." (PMID 35677043, 2022). "Polyphenols extracted from Artemisia annua can inhibit the phenotype of CSC, mediate the phosphorylation of MMP-9 and STAT3, and exhibit anticancer effects in human breast cancer cells." (PMID 36686745, 2022). "MMP-1 was reported to be upregulated in Adriamycin MCF-7 breast cancer cells, along with MMP-2 and MMP-9." (PMID 35586209, 2022). "In a study conducted on patients with breast cancer, a correlation was observed between ER−α and two typical EMT markers, MMP9 and vimentin." (PMID 36232636, 2022). "Meanwhile, RUNX2 expression was increased by increasing the expression of vascular endothelial growth factor, matrix metalloproteases (MMP2, MMP9, and MMP13), and bone sialoprotein (BSP) in breast cancer metastatic cells." (PMID 36092942, 2022). "NF-κB signaling pathway regulates the expression of its downstream target genes, including MMP9, TNFα, uPA and IL8, thus promoting the invasion and metastasis of breast cancer cells." (PMID 36463222, 2022). "In breast cancer, IL-1β has also been shown to up-regulate matrix metalloproteinase (MMP) 2, and MMP9, thereby promoting invasiveness and vasculogenic mimicry of tumour cells." (PMID 36353102, 2022). "Muscone derivative ZM-32 attenuated the stabilizing effect of RNA-binding protein HuR toward Vegf-a and Mmp9 mRNA, thus resulting in downregulation of VEGF-A and MMP-9 expression in HUVECs and breast cancer MDA-MB-231 cells." (PMID 35784750, 2022). "Breast Cancer: curcumin down regulate of NF-jB, AP-1, COX-1, and –2, VEGF, fibroblast growth factor (FGF), cyclin E, IL-6, and –11, TGF-b, MMP-2, MMP-9, and MMP-13, the upregulation of tissue inhibitor of metalloproteinase-1." (PMID 36712505, 2022). "In the context of breast cancer brain metastasis, we also found BRD4 silencing caused downregulation of two downstream target molecules, Shh and Gli, while BRD4 overexpression improved their expression, suggesting that BRD4 may promote MMP9 expression through SHH signaling pathway in 231-BR cells." (PMID 34421353, 2021).
breast carcinoma (continued). "Taken together, these results suggest that BAALC overexpression in breast cancer cells leads to phosphorylation of FAK and secretion of MMP-9, resulting in increased capacity for migration and invasion and ultimately higher risk of metastasis." (PMID 33968759, 2021). "Eugenol treatment shows an anti-metastatic effect by reducing the invasion and migration of MDA-MB-231 breast cancer cells mostly by reducing the expression of MMP-2 and MMP-9." (PMID 34502165, 2021). "Analysis with ONCOMINE demonstrated that the mRNA expression levels of MMP9 and NFKB1 were significantly higher in metastatic breast cancer cells than in normal tissues." (PMID 34335799, 2021). "Western blot results showed that the expression of VE-cadherin, VEGFR-1, MMP-9, and MMP-2 was increased in both breast cancer cells." (PMID 34055597, 2021). "Taken together, we demonstrated that ORM1 promotes the malignant phenotype of breast cancer by upregulating the expression of MMP-2 and MMP-9, thus activating the AKT/ERK signaling pathway." (PMID 34654351, 2021). "Our previous work has shown the involvement of MMP-3, MMP-9, TIMP-3, and TIMP-4 in response to radiotherapy in breast cancer patients, suggesting their utility as potential prognostic and predictive biomarkers for this pathology." (PMID 34445715, 2021). "In summary, ORM1 promotes the malignant phenotype of breast cancer by upregulating the expression of MMP-2 and MMP-9." (PMID 34654351, 2021). "In breast cancer, ARPC2 expression significantly upregulated the expression of vimentin, N-cadherin, MMP-9, ZEB1, and MMP-3, activated the TGF-β pathway, and eventually led to epithelial–mesenchymal transition (EMT)." (PMID 34307456, 2021). "In another study, Berberine was found to inhibit TNF-α-induced matrix metalloprotein 9 (MMP-9) and cell invasion through inhibiting activating protein-1 (AP-1) in MDA-MB-231 human breast cancer cells." (PMID 34497528, 2021). "Treatment with sHA, however, lead to the downregulation of MT1-MMP, known to be involved in breast cancer cell migration and invasion, as well as the downregulation of MMP2 and MMP9, two MMPs with pivotal role in ECM degradation." (PMID 34944559, 2021). "A previous study demonstrated that tangeretin inhibits metastasis in rat mammary carcinoma induced by 7,12-dimethylbenz (α) anthracene by downregulating MMP2, MMP9, and VEGF." (PMID 34335799, 2021). "In MDA-MB-231 breast cancer cells, DADS, besides similar effects on MMP-9, showed other abilities: inhibition of cell migration and invasion, reversion of EMT, and finally induction of apoptosis through the modulation of the β-catenin signaling pathway." (PMID 34572548, 2021). "A recent study of the expression of MMP-9 and VEGF(FLT1) in breast cancer patients found their correlation significant enough to propose these genes as prognostic indicators." (PMID 33909629, 2021). "Downregulating the expression of ORM1 reversed the malignant phenotype of breast cancer cells by targeting MMP-2 and MMP-9 and activating the AKT/ERK signaling pathway." (PMID 34654351, 2021). "Prior studies have revealed the CCA-1.1 parent compound PGV-1 exerted an anti-migratory effect and lowered the MMP-9 and Rac-1 expressions in TNBC 4T1cells; this phenomenon was also presented in HER2+ breast cancer cells." (PMID 34181339, 2021). "Calycosin treatment decreased the expression of CD147, MMP-2, and MMP-9 transcripts and proteins in BATF-overexpressing breast cancer cells." (PMID 34096887, 2021). "A flavonoid found in various food, fisetin, reduced cell migration and colony formation in 4T1 and JC breast cancer cells by decreasing the enzyme activities of matrix metalloproteinases (MMP-2 and MMP-9)." (PMID 35126099, 2021). "It has also been reported that 12-O-tetradecanoylphorbol-13-acetate (TPA)–induced MMP-9 expression is also decreased by CO, Fe3+, and bilirubin in MCF-7 breast cancer cells." (PMID 34483918, 2021).